CCR7 (C-C motif chemokine receptor 7)
Diseases named in the same sentence as CCR7 in open-access papers (continued):
Sharing a sentence is not in itself a finding about the gene and the disease.
asthma (19 papers, 2004 to 2025). "CCR1 and CCR7 are chemokine receptors in Th2/type 2 pathway, which is thought to be the dominant inflammatory pathway underlying severe asthma." (PMID 33602227, 2021). "Taking these data together, we concluded that omalizumab treatment results in decreased FcεRI expression as well as decreased expression of CCR7, HLA-DR, and costimulatory molecules on both blood mDC and pDCs of asthma patients." (PMID 40697948, 2025). "In the present study, various cytokines, including IgE, were found to be involved in allergy-induced asthma and their expression level decreased following knockdown of CCR7." (PMID 31545493, 2019). "CCR7 has important roles in DC-mediated immune inflammation and immune tolerance in patients with allergy-induced asthma." (PMID 31545493, 2019). "On the contrary, the proportion of sialyl LeX positive FOXP3+CCR7+CCR4− Treg cells among CD4+ T cells was lower in moderate-to-severe asthma compared with healthy controls (post hoc p < 0.05)." (PMID 31222115, 2019). "After modification of the DCs using these viral vectors, the therapeutic effects of CCR7-guided CTLA4Ig were evaluated in a mouse asthma model." (PMID 25177863, 2014). "In asthma, CCR3 and 7 are expressed by airway smooth muscle (ASM) and CCR7 has been implicated in the development of ASM hyperplasia." (PMID 19735481, 2009). "Previous studies have found that both TNF, SPI1, and CCR7 were up-regulated in severe asthma." (PMID 35645813, 2022). "And the proportion of CCR7+ memory CD4+ T cell was negatively correlated with improved pulmonary tests and significantly associated with disease severity scores and IgE levels, showing significant clinical implications in asthma and eosinophilic inflammation." (PMID 35000593, 2022). "CCR7 could also participate in the airway remodeling of severe asthma by enhancing fibrocyte transmigration." (PMID 33602227, 2021). "CCR7 is involved in the migration and maturation of dendritic cells (DCs), which could facilitate the development of asthma." (PMID 33602227, 2021). "The present results suggested that a decrease in the expression level of CCR7 may suppress the immune response in patients with allergy-induced asthma." (PMID 31545493, 2019). "The present results suggested that CCR7 may serve an important role in the regulation of the immune response in DC-induced asthma." (PMID 31545493, 2019). "Accordingly, the frequency of CCR4+CCR7+ memory CD4+ T cells correlated with asthma severity." (PMID 29507584, 2018). "In addition, the percentage of circulating CCR4+CD45RA−CD45RO+CCR7+ CD4+ T cells in patients correlated with asthma severity, as measured with % predicted FEV1 scores." (PMID 29507584, 2018). "Due to the heterogeneity of asthma phenotypes and clinical variation, we next investigated whether the increase of CCR7+ memory CD4+ T cells is a common feature of different asthma subtypes." (PMID 29507584, 2018). "In conclusion, CTLA4Ig-modified DCs exhibited a therapeutic effect on asthma, and CCR7 may guide DC homing." (PMID 25177863, 2014). "Additional evidence that these cells may be of fibrocytic origin comes from a study that showed that CCR7 is expressed in the myofibroblasts in the bronchial mucosa of patients with asthma." (PMID 21219601, 2011). "In addition, findings about the role of CCR7 in immune tolerance in allergy-induced asthmatics may provide ideas for the treatment of severe asthma." (PMID 33602227, 2021). "CTLA4Ig-modified DCs exhibited a therapeutic effect on asthma, and CCR7 may guide DC homing." (PMID 25177863, 2014). "CCR7 expression was shown to be dependent on type 1 IFNs and was correlated with Th2 cell induction in a house dust mite (HDM) asthma model and during S. mansoni infections, suggesting a role for type 1 IFNs in ω1-reduced DC migration." (PMID 39186814, 2024). "Because these ligands interact with CCR7, the serum levels of dissociated CCL21 were lower in patients with asthma than in healthy controls." (PMID 33503170, 2021).
asthma (continued). "The overall eosinophil levels were higher in patients with asthma, and they expressed CCR7 on their surface; all these factors influence serum CCL21 levels in patients with asthma." (PMID 33503170, 2021). "We also found that the differences of sialyl LeX positive and sialyl 6-sulfo LeX positive cells among memory Th cells in childhood asthma exist predominantly in CCR4+CCR7− effector memory Th subset, instead of in CCR7+ central memory Th subset." (PMID 31222115, 2019). "Improved characterization of the roles of the memory Th cells and Treg cells in asthma, especially their CCR7+ and CCR4+ subsets, could improve our understanding of asthma immunology." (PMID 31222115, 2019). "In the present study, CCR7 knockdown increased the protein expression levels of IL-10 and TGF-β in allergy-induced asthma, suggesting that CCR7 may serve an important role in immune tolerance in allergy-induced asthma." (PMID 31545493, 2019). "Isolation of total and the CCR7+ subset of sialyl LeX positive FOX3+ CD25+ Treg cells in the airway specimens of asthma patients and utilization of in vivo model would help further clarify the potential role of sialyl LeX on Treg cells in asthma." (PMID 31222115, 2019). "Current common asthma therapeutics (including corticosteroids) were not able to affect the frequency of CCR4+CCR7+ memory CD4+ T cell subsets." (PMID 29507584, 2018). "We have demonstrated that β2-AR activation by salmeterol leads to a reduction in the proliferation, myofibroblastic differentiation and CCR7 expression in fibrocytes from healthy subjects and patients with non-severe asthma." (PMID 29162108, 2017). "Salmeterol reduced the proliferation, myofibroblastic differentiation and CCR7 expression of fibrocytes from healthy subjects and non-severe asthma patients." (PMID 29162108, 2017). "We determined the effect of the β2-AR agonist, salmeterol, in the presence or absence of the corticosteroid dexamethasone on the number, differentiation potential, and CCR7 and β2-AR expression in fibrocytes from patients with non-severe and severe asthma and healthy subjects." (PMID 29162108, 2017). "Moreover, after observing increased production of CCL19 and its receptor CCR7, these investigators suggested that the CCL19 - CCR7 axis may play a role in the recruitment of fibrocytes to the lungs in patients with asthma." (PMID 21219601, 2011).
colorectal cancer (19 papers, 2012 to 2025). A primary or metastatic malignant neoplasm that affects the colon or rectum. "In colorectal cancer, CCR7 expression was associated with cancer progression, metastasis to the lymph nodes, and decreased patient survival 157,158." (PMID 36118530, 2022). "In ulcerative colitis, which was associated with elevated levels of CCR7, the receptor was postulated as an inflammatory marker of disease progression to colorectal cancer." (PMID 35203305, 2022). "The chemokine CCL19 has been demonstrated to inhibit angiogenesis in colorectal cancer through a CC-chemokine receptor 7 (CCR7)-dependent manner." (PMID 38053093, 2023). "Studies have found that CCR7 is closely related to the prognosis of various cancers, such as squamous cell carcinoma of the tongue and floor of the mouth, bladder cancer, and colorectal cancer." (PMID 35996545, 2022). "High CCR7 expression level is related to lymphatic tumor metastasis and prognosis in gastric as well as colorectal cancer." (PMID 36243683, 2022). "A recent article confirmed that colorectal cancers expressed increased levels of CCR7, which correlated with tumor size and poorer overall survival; notably, this elevated expression was commonly associated with primary tumors of the rectum." (PMID 35203305, 2022). "In contrast, in colorectal cancer patients we observed a significantly higher number of Treg cells with a CCR7+CD45RA+ naïve phenotype." (PMID 22276195, 2012). "Furthermore, in tissue sections of liver tumors from patients with colorectal cancer liver metastases, the high expression of both CCR7 and CCL21 suggests that CCR7/CCL21 signaling promotes colorectal cancer liver metastasis." (PMID 40038879, 2025). "High CCR7 positive cell density was significantly related to prognosis in colorectal cancer." (PMID 35395711, 2022). "In colorectal cancer, truncated CCR7 led to growth and survival advantages of cancer cells." (PMID 35203305, 2022). "The link between CCR7 expression and colorectal cancer has shown variable results." (PMID 35203305, 2022). "Chemokine CCL19 inhibits colorectal cancer (CRC) angiogenesis in a CCR7-dependent manner." (PMID 31143705, 2019). "Therefore, future studies in colorectal cancer tissues are warranted and may shed new light on the involvement of CCR7 signaling in colorectal tumorigenesis or other cancer types that depend on the Wnt/β-catenin pathway." (PMID 23055828, 2012). "In colorectal cancer cells, CCL19 activates CCR7, thereby inducing miR-206 upregulation, which suppresses angiogenesis to inhibit the ERK/MAPK-HIF-1-VEGF pathway." (PMID 38552222, 2024). "Here we report that functional Treg cells of a naïve phenotype - as determined by CCR7 and CD45RA expression - are significantly expanded in colorectal cancer patients." (PMID 22276195, 2012). "PB derived CD4+ T cells from two colorectal cancer patients and two age-matched healthy individuals were sorted according to their CD25, CCR7 and CD45RA expression into the appropriate CD4+CD25high Treg-cell subsets, namely Tnaïve, TCM, and TEM." (PMID 22276195, 2012). "Further analysis of colorectal cancers revealed that CCR7 expression was highly variable, although rarely absent from patient tumor specimens." (PMID 35203305, 2022). "In colorectal cancer, where CCR7 does not correlate with survival, the receptor is found within the cytoplasm, where it cannot signal in response to ligands." (PMID 35203305, 2022). "In the human colorectal carcinoma cell line, SW480, CCR7 knockdown using shRNA led to reduced MMP-9 levels that, when tested in a xenograft mouse model, lowered colon cancer metastasis and increased animal survival when compared to CCR7-expressing tumor cells." (PMID 35203305, 2022).
colorectal cancer (continued). "The cellular function of the truncated form of CCR7 was not determined although it was hypothesized to confer a growth and/or survival advantage to the colorectal cancer cells." (PMID 35203305, 2022).
prostate carcinoma (19 papers, 2012 to 2025). A carcinoma that arises from epithelial cells of the prostate gland. "For instance, in bladder and prostate cancers, expression of CCR7 was linked to elevations in MMPs and more aggressive tumors." (PMID 35203305, 2022). "MicroRNA Let-7a expression is associated with induction of EMT in prostate cancer through directly suppressing C-C chemokine receptor type 7 (CCR7) and MAPK pathway." (PMID 31547193, 2019). "Five SNPs detected in CCL5, CCR5 and CCR7 were significantly associated with prostate cancer risk among all study participants; however, only three markers survived adjustments for potential confounders and multiple hypothesis testing." (PMID 23168091, 2012). "Several papers have highlighted the role of CCR7 in the progression and metastasis of colorectal, gastric, esophageal, and prostate cancers." (PMID 40299690, 2025). "In a case study, the same group showed intense antibody staining of CCR7 in prostate cancer tissue, which was the first time that high CCR7 had been reported and that likely explained the positive lymph node status of the patient." (PMID 35203305, 2022). "In the same PC-3 xenograft mouse model, CCR7 knockdown decreased prostate cancer tumor volumes compared to controls, suggesting that the CCR7 pathway affects tumor proliferation." (PMID 35203305, 2022). "Tumors that typically show low metastasis to lymph nodes, such as prostate cancer, also had a propensity to migrate to lymph nodes in cases where CCR7 expression was identified." (PMID 35203305, 2022). "Despite the relatively modest incidence of CCR7 effects on the progression of prostate cancer, it was noted in vitro that siRNA against CCR7, in PC-3 prostate adenocarcinoma cells, not only silenced CCR7 but also inhibited VEGF and MMP-9 protein expression." (PMID 35203305, 2022). "The medium of murine prostate cancer cells inhibits migration of BM-DCs and splenic cDCs through the activation of CC chemokine receptor-7 (CCR7) ligand CCL19 in vitro, and migration to draining lymph nodes in vivo." (PMID 33271839, 2020). "CCL21, a ligand of CCR7 that is secreted by fibroblastic reticular cells in lymph nodes and is abundant in the T-cell zone of the lymph node, was found to promote prostate cancer cell migration via protein kinase p38 phosphorylation." (PMID 30871130, 2019). "We found that murine prostate cancer cell line RM-1-conditioned medium impaired chemotactic movement of marrow-derived DCs and splenic cDCs toward CC chemokine receptor-7 (CCR7) ligand CCL19 in vitro and migration to draining lymph gland in vivo." (PMID 29850633, 2018). "In this study, we performed next-generation sequencing-based gene expression analysis in peripheral blood from prostate cancer patients obtained pre- and post-radiotherapy and found six independently down-regulated genes including CCR7, FCGR2B, BTLA, CD6, CD3D, and CD3E." (PMID 36291815, 2022). "Prostate cancer cell lines were used to show that low expression of TNF-α induced CCR7 expression." (PMID 35203305, 2022). "In this study, we performed gene expression analysis on peripheral blood from prostate cancer patients obtained post- radiotherapy and showed that 6 genes, including CCR7, FCGR2B, BTLA, CD6, CD3D, and CD3E, were down-regulated by a range of 1.5–2.5-fold as compared to pre-radiotherapy samples." (PMID 36291815, 2022). "Moreover, the silencing of CCR7, a protein involved in angiogenesis, inhibits prostate cancer cell proliferation, migration and invasion." (PMID 36291815, 2022). "Further studies have investigated CCR7 effects on prostate cancer cell growth." (PMID 35203305, 2022). "CCR7 upregulation also induces prostate cancer cell migration." (PMID 34485395, 2021). "CCR7 expression has been shown to be positively correlated with lymphatic metastasis and a poor prognosis in squamous cell, oral and oropharyngeal squamous cell carcinoma and breast, colorectal, esophageal and prostate cancers." (PMID 23761820, 2013).
prostate carcinoma (continued). "Peng first examined CCL19 and CCR7 expression in samples from prostate cancer and found that CCL19 and CCR7 were significantly overexpressed in all five prostate cancer cell lines he detected." (PMID 30430424, 2019). "We screened cells from our cell bank for the expression of chemokine receptors CCR7 and CXCR4 and found that PC-3 (human prostate cancer) cells express high levels of both CXCR4 and CCR7." (PMID 28432337, 2017). "The NF-κB pathway was recently reported to be situated downstream of the SLC/CCR7 axis in hepatocellular carcinoma and downstream of the TGF-β1/TGF-βR axis in prostate cancer." (PMID 26176983, 2015). "Overall, the data supports mechanisms for CCR7-mediated prostate cancer lymphoid migration, although these pathways are likely not active in many prostate cancer patients." (PMID 35203305, 2022). "We observed that human prostate cancer cells (PC-3, DU145, LNCaP, and LNCaP-SF) express both TNF-α and CCR7 and that low concentrations of TNF-α can induce CCR7 expression in prostate cancer cells through phosphorylation of extracellular signal-regulated kinases in an autocrine manner." (PMID 30871130, 2019). "Furthermore, TNF-α leads to the induction of CCR7 expression and the CCL21/CCR7 axis may increase the metastatic potential of prostate cancer cells in lymph node metastasis." (PMID 35517503, 2022).
Sepsis (19 papers, 2017 to 2025). Sepsis is defined as life-threatening organ dysfunction caused by a dysregulated host response to infection. "Patients with sepsis showed increased CCR7 expression on circulating monocytes, and a bioinformatics analysis of whole blood leukocyte RNA expression in datasets of patients with CAP-induced sepsis implicated CCR7 as a gene driving sepsis development." (PMID 38077404, 2023). "Astaxanthin can downregulate CCR7 expression impeding lipopolysaccharide-induced DC migration, which is beneficial in the treatment of sepsis." (PMID 40426888, 2025). "Recent studies have further elucidated the roles of key downregulated genes-Ccl4, Ccr7, and Ebi3-in inflammation and sepsis-induced cardiac injury." (PMID 41169382, 2025). "Age positively correlated with the percent of central memory CD4+ (CCR7+CD45RA-) T cells in sepsis (r2 = 0.36, p=0.001) and AOD (r2 = 0.46, p=0.01)." (PMID 39935482, 2025). "This aligns with previous findings suggesting that CCR7 deficiency can exacerbate skin inflammation, reinforcing ARG1-CCR7’s role as a B and T cell marker in sepsis." (PMID 39710434, 2024). "Conversely, the difference in expression levels between ARG1 and CCR7 was consistently higher in sepsis samples compared to normal samples." (PMID 39710434, 2024). "Yang found that CCR7 was significantly changed in patients with sepsis compared with matched controls." (PMID 36199375, 2022). "An immune cell-specific study has found that MMP9, ARG1, CXCL3, SOCS3, CCR7, and IL-10 are differentially expressed in T cells and monocytes from sepsis patients compared with healthy individuals." (PMID 35721566, 2022). "Through searching the sepsis-related publication of the key genes, CCR7, CXCR3, FYN, CEACAM1, CD81, AMPH, HLA-DMA, and G protein-coupled receptors (GPR18) were considered to be key genes." (PMID 34484417, 2021). "Tier 2 sepGIKs included 89 sepGIKs (399 pairs), such as FFAR2 (free fatty acid receptor 2), CCR7 (C-C chemokine receptor type 7), HK3 (hexokinase 3), and IRAK3 (interleukin-1 receptor-associated kinase 3), which were differentially expressed in at least 14 sepsis datasets." (PMID 40761792, 2025). "During sepsis, characterized by a dysregulated immune response to infection, alterations in the expression of CCR7 may be attributed to changes occurring within these cells." (PMID 39710434, 2024). "Li Y found that CCR7 might participate in the mechanism of community-acquired pneumonia (CAP) with sepsis." (PMID 36199375, 2022). "In this study, the key genes downregulated during sepsis also encoded proteins responsible for the immune response, including the expression of antigen-presenting cells, the regulation of cytokine production, and the activation of B and T lymphocytes (i.e., CD79A, HLA-DQB2, PLD4, and CCR7)." (PMID 37298316, 2023). "Upregulated genes identified in sepsis Th17 cell compared to bacteraemia cells were involved in T cell differentiation (ITGA4 and CCR7; 0.80 and 0.41log2FC, respectively), activation, and antigen receptor signalling (CD3G; 0.98log2FC) pathways." (PMID 41208955, 2025). "Age was inversely correlated with the percent of naïve (CCR7+/CD45RA+) CD4+ T cells in AOD (r2 = 0.49, p=0.008) and sepsis (r2 = 0.19, p=0.024)." (PMID 39935482, 2025). "There were less central memory (CCR7+/CD45RA-) CD4+ and CD8+ T cells in sepsis compared to healthy (p=0.02 and 0.04, respectively)." (PMID 39935482, 2025). "Conversely, sepsis samples consistently exhibited high ARG1 expression and low CCR7 expression, while normal samples consistently displayed high CCR7 expression and low ARG1 expression across the various datasets." (PMID 39710434, 2024). "Both PPI and lncRNA-miRNA-mRNA networks confirmed that ETS proto-oncogene 1 (ETS1), C-C motif chemokine receptor 7 (CCR7) and CD5 are key genes of the ceRNA network in sepsis." (PMID 36457745, 2022).